HBD (hemoglobin subunit delta)
Description:
Involved in oxygen transport from the lung to the various peripheral tissues.
Synonyms: HBK
Tractability: Small molecule: a structure with a bound ligand is known.
Gene: Protein-coding gene on chromosome 11 (5,232,678 to 5,243,657, reverse strand). Ensembl gene ENSG00000223609.
Pathways (Reactome):
Hemostasis: Factors involved in megakaryocyte development and platelet production
Gene Ontology:
Molecular function: protein binding; heme binding; hemoglobin alpha binding; oxygen carrier activity; oxygen binding
Biological process: oxygen transport; carbon dioxide transport; erythrocyte development
Cellular component: blood microparticle; hemoglobin complex; cytosol; haptoglobin-hemoglobin complex
Genetic constraint (gnomAD): Loss-of-function variants: 11 observed, 11.35 expected, observed/expected ratio (o/e) 0.97, 90% interval 0.61 to 1.59. The upper end of that interval is the gene's LOEUF score, 1.59, which puts it in group 6 of 6, group 1 being the genes least tolerant of losing a copy. Missense variants: 188 observed, 180.64 expected, observed/expected ratio (o/e) 1.04, 90% interval 0.92 to 1.17. Synonymous variants: 83 observed, 69.47 expected, observed/expected ratio (o/e) 1.19, 90% interval 1 to 1.43.
Homologues: Orthologues: chimpanzee HBD (99% identical), zebrafish hbaa2 (39% identical), zebrafish hbaa1 (39% identical), zebrafish si:ch211-5k11.8 (39% identical), zebrafish hbae5 (38% identical), zebrafish hbae1.1 (37% identical), zebrafish hbae1.2 (37% identical), zebrafish hbae1.3 (37% identical), zebrafish hbae3 (37% identical), Drosophila melanogaster glob1 (21% identical), Caenorhabditis elegans glb-34 (15% identical), Caenorhabditis elegans glb-14 (14% identical). Paralogues in human: HBB (93% identical), HBE1 (73% identical), HBG2 (72% identical), HBG1 (71% identical), HBA1 (42% identical), HBA2 (42% identical), HBQ1 (39% identical), HBZ (37% identical), HBM (35% identical), CYGB (30% identical), MB (24% identical).
Diseases named in the same sentence as HBD in open-access papers:
HBD is named in the same sentence as 66 diseases in open-access papers, as found by Europe PMC text mining. Sharing a sentence is not in itself a finding about the gene and the disease. The quoted sentences say what the papers report.
thalassemia (8 papers, 2010 to 2026). An inherited blood disorder characterized by a decreased synthesis of one of the polypeptide chains that form hemoglobin. "The trends described in this study are also noted for many other mutations of the globin genes, including HbC, HbE, HbD, and numerous α-thalassaemia and β-thalassaemia variants, which should also be carefully considered." (PMID 24748392, 2014). "A co-existence of β-thalassemia heterozygous state with structural hemoglobin variants like HbE, HbS, and HbD also leads to thalassemia intermedia phenotype." (PMID 23350016, 2013). "Apart from β- thalassaemia, nine additional variants were encountered; HbS (2.8%), HbE (2.5%) and HbD (1.1%) being the most common variants present." (PMID 21150000, 2010). "Although we focus on HbS, various other common haemoglobin variants, including HbC, HbE, HbD, and a large range of α-thalassaemia and β-thalassaemia mutations, are also spreading globally because of increasing population movements, and the same principles as for HbS apply." (PMID 24748392, 2014). "Of those tested with hemoglobin electrophoresis, 13 (16.05%) were negative, while 60 (74.08%) tested positive for SCD, excluding cases with thalassemia, HbE, and HbD for AI analysis." (PMID 41322744, 2025). "In the present study, no HBD variant was detected either in thalassemia patients or carriers by NGS analysis." (PMID 37580329, 2023).
COVID-19 (5 papers, 2022 to 2024). A disease caused by infection with severe acute respiratory syndrome coronavirus 2. "Previous studies primarily focused on hBD expression in the serum of COVID-19 patients, which cannot be directly compared with the expression profiles in the nasopharynx." (PMID 39339947, 2024). "The data in our possession show an increase in HNP-1, HBD-1 and HBD-4 in both serum and cord blood of patients with the COVID compared to controls; in addition, the levels of HBD-4, inducible defensin, found to be higher in the cord blood taken from pregnant women with COVID-19." (PMID 35408809, 2022). "These proteins either act as positive regulators of cell death (HBG1, HBB, HBD, and HBA1) or are involved in the cellular response to tumor necrosis factor (FABP4, GPD1, THBS1, ASS1, and PCK2), suggesting that apoptosis may be an important cause of heart failure in patients with COVID-19." (PMID 38087340, 2023). "The COVID-19 convalescents had significantly elevated immunoglobulins, Orosomucoid 2 (ORM2), peroxiredoxin-2 (PRDX2), hemoglobin subunits (HBD, HBB and HBA1), as well as proteins involved in cholesterol transport such as cholesteryl ester transfer protein (CETP) and apolipoprotein A1 (APOA1)." (PMID 38396092, 2024). "In comparison, clusters D and E had proteins with higher levels in COVID-19 convalescents, e.g. immunoglobulins playing a role in antigen recognition (e.g. IGKV1-27, IGKV1-39, IGHV1-46, IGLV3-1, and PRDX2), hemoglobin subunits (e.g. HBB, HBA1, and HBD), and carbonic anhydrase (CA1)." (PMID 38396092, 2024). "We found that the levels of CK-MB, LDH-L, and α-HBD could predict the mortality rate very well in COVID-19 patients without hypertension." (PMID 36326681, 2022).
sickle cell anemia (5 papers, 2016 to 2023). "A previous report on the genetic correction of a beta hemoglobin gene to treat sickle cell disease in human hematopoietic stem/progenitor cells using ZFNs showed off-target cleavage in the highly homologous, but functionally dispensable, HBD gene." (PMID 29482624, 2018). "In case of these changes, in addition to the normal HbA0 glycation to form HbA1c, other glycation products derived from HbC (African populations), HbD (indigenous populations), HbE (Asian populations), or HbS (sickle cell anemia) could be formed." (PMID 27471550, 2016). "In HbS/S patients with sickle cell anemia (SCA), there are two peaks, one representing HbS and the other Hb-Voxelotor fraction, the latter having similar mobility as native HbD in HPLC assays." (PMID 37153104, 2023).
hemoglobinopathies (4 papers, 2011 to 2025). "Structural haemoglobinopathies are caused by CNVs affecting HBD and HBB, leading to a fusion of the genes, which gives rise to abnormal hybrid haemoglobin variants." (PMID 36555557, 2022). "Mutation study for the HBB gene was conducted for four ß-haemoglobinopathies, HbC [β6; AA Glu→Lys (E→K)], HbD [β121; AA Glu→Gln (E→Q)], HbE [β26; Glu→Lys (E→K)], and HbS [β6; Glu→Val (E→V)]." (PMID 22028795, 2011). "Structure analysis was performed on the key mutations that occur in the native protein coded by the HBB gene that causes hemoglobinopathies such as: HbC (E→K), HbD (E→Q), HbE (E→K) and HbS (E→V)." (PMID 22028795, 2011). "Integrating HbD detection into screening programmes and genetic counselling can help prevent hemoglobinopathies." (PMID 40373022, 2025). "We demonstrated the clinical utility of molecular phenotyping in clinical hemoglobinopathies by mapping out the spectrum of heterozygous HbE, HbD and a heterozygous beta thalassemia (HBB:c.27_28insG) variants." (PMID 32985608, 2020).
periodontal disease (4 papers, 2015 to 2024). "The salivary HNP and hBD levels differed in terms of their correlation to the extent of periodontal disease and tooth loss in the elderly." (PMID 36769624, 2023). "On the one hand, hBD levels are expected to increase in patients with periodontal diseases, as the infectious stress and inflammatory response increase during these diseases." (PMID 39204254, 2024). "The ability of a black tea extract and theaflavins to exert antibacterial activity against major periodontopathogens as well as to attenuate the secretion of IL-8, and to induce hBD secretion in oral epithelial cells suggest that these components may have a beneficial effect on periodontal disease." (PMID 26581041, 2015). "Higher levels of hBD 1were observed in healthy sites of patients without periodontal disease than inhealthy sites of patients with periodontitis (p<0.0001)." (PMID 36043572, 2022).
psoriasis (4 papers, 2006 to 2020). An autoimmune condition characterized by red, well-delineated plaques with silvery scales that are usually on the extensor surfaces and scalp. "The antimicrobial peptides HBD-2 and LL-37 are normally produced by keratinocytes in response to inflammatory stimuli such as psoriasis or injury." (PMID 27200138, 2016). "Since our findings revealed that NETs were present within psoriatic epidermis in close proximity to keratinocytes which expressed HBD-2, we next investigated whether netting neutrophils from psoriasis patients may induce HBD-2 expression in epidermal keratinocytes." (PMID 27493143, 2016). "hBD is induced by TNF-α and IFN-γ, which are highly expressed in psoriasis lesional skin." (PMID 32947991, 2020). "The hBD gene expression patterns observed in BCCs do not appear to be substantially different from those seen in inflammatory conditions such as atopic dermatitis and psoriasis." (PMID 16796735, 2006).
beta thalassemia (3 papers, 2020 to 2024). Beta-thalassemia (BT) is characterized by deficiency (Beta+) or absence (Beta0) of synthesis of the beta globin chains of hemoglobin (Hb). "Five genes mapped to hemoglobin subunits (HBG1, HBG2, HBE1, HBB and HBD) involved in beta thalassemia and fetal hemoglobin quantitative trait locus 1 diseases." (PMID 38627641, 2024). "In addition to the sickle trait gene (HBB), our mapping strategies identified other members of beta globin gene cluster that cause various forms of beta-thalassemia (HBE1, HBD, HBG, and HBG2)." (PMID 34868193, 2021).
periodontitis (3 papers, 2012 to 2024). An acute or chronic inflammatory process that affects the tissues that surround and support the teeth. "Previous studies demonstrated that the single-nucleotide polymorphisms of TLRs are associated with an increased colonization of periodontitis-associated bacteria, a risk of developing periodontitis, and decreased hBD levels." (PMID 39204254, 2024). "Considering the association of CD14 genetic polymorphisms with the severity of chronic periodontitis, the present study investigated for the first time the potential association of both hBD and CD14 polymorphisms and their serum levels with chronic periodontitis in Chinese subjects." (PMID 23046822, 2012).
Sepsis (3 papers, 2019 to 2022). Sepsis is defined as life-threatening organ dysfunction caused by a dysregulated host response to infection. "Moreover, a recent study in adults with severe sepsis showed decreased mRNA expression and plasma levels of HBD-3, suggestive of a decreased synthesis of this AMP during severe sepsis." (PMID 36079001, 2022). "Besides, HBD expression has been associated with decreased H2O2-induced damage to the nuclear and the mitochondrial DNA of PBMCs of patients with sepsis." (PMID 34504491, 2021). "We conclude that the heme and hemoglobin metabolism is modulated during sepsis, with emphasis in the four genes ALAS2, AHSP, HBD, and CA1, common to the three datasets." (PMID 31396396, 2019). "Thus, four common genes were found upregulated in the three datasets (ALAS2, AHSP, HBD and CA1), notably, they were most significantly expressed in follow-up samples of patients who survived sepsis." (PMID 31396396, 2019).
adenoma (2 papers, 2020 to 2024). A neoplasm arising from the epithelium. "In the analyzed study, the expression of three hBD subtypes was compared between healthy salivary gland tissue, chronically inflamed salivary glands, pleomorphic adenoma tissues, and adjacent adenoma tissues." (PMID 39684268, 2024). "Meanwhile, hemoglobin (HBA1, HBB or HBD) was not significantly differential between high‐risk adenomas and controls, and subsequently it was not selected in any of the biomarker panels, which is in line with the limited sensitivity of FIT for adenomas." (PMID 31784980, 2020).
asthma (2 papers, 2021 to 2022). "In this regard, when analyzing the level of hBD expression in asthma, it is necessary to take into account the possibility of genetic polymorphisms of AMP genes, which can aggravate the course of asthma." (PMID 35269641, 2022). "In bronchial epithelial cells collected by bronchoscopic brush biopsy, the expression of hemoglobin genes (HBA1, HBA2, HBB and HBD) was strongly correlated with Pre-bronchodilator FEV1 PP in patients with asthma enrolled in SARP I&II but not in controls." (PMID 34326365, 2021).
glioma (2 papers, 2014 to 2025). A benign or malignant brain and spinal cord tumor that arises from glial cells (astrocytes, oligodendrocytes, ependymal cells). "In the Glioma/NC group, 8 proteins (COL1A1, PRL, VWF, HBD, SF3B1, NME3, RRBP1, and CSRP1) were selected, with an AUC of 0.892 in the training set and 0.871 in the validation set (accuracy: 78.5%)." (PMID 39716938, 2025). "Major discriminator between high-grade and low-grade tumors included CRYAB, IPYR, TPIS, PEA15, PSD13, GFAP, IDH3A, 6PGL, PHP14, KCRB as overexpressed in low-grade gliomas; HCD2, HBA, HBD as overexpressed in high-grade GBM." (PMID 25050814, 2014). "Twelve major discriminators between low- and high-grade gliomas were identified: HCD2, HBA and HBD were up-regulated in high-grade gliomas, whereas expression levels of CRYAB_b, IPYR, TPIS, PEA15, PSD13, GFAP, IDH3A, 6PGL and PHP14 were found to be higher in low-grade than in high-grade tumors." (PMID 25050814, 2014).
HIV-1 infection (2 papers, 2017 to 2021). The type species of lentivirus and the etiologic agent of acquired immunodeficiency syndrome (AIDS). "It is also possible that hBD-2PTD and/or hBD-3PTD may inhibit HIV-1 infection in CD4+ T lymphocytes, CD68+ macrophages, and CD1c+ DC in the tonsil tissue." (PMID 34696473, 2021). "In this study, we characterized HBD expression in vivo during early and chronic HIV-1 infection." (PMID 28253319, 2017).
Insulin resistance (2 papers, 2022 to 2023). Increased resistance towards insulin, that is, diminished effectiveness of insulin in reducing blood glucose levels. "In this sense, we have found an upregulation of different genes related to hypoxia regardless of the degree of insulin resistance, such as ANGPTL4, LPL, S100A8, SLC11A2, HBB, HBA2, and HBD." (PMID 35625760, 2022).
myocardial ischemia (2 papers, 2017 to 2024). A disorder of cardiac function caused by insufficient blood flow to the muscle tissue of the heart. "Our study showed that STDP had a dose-dependent inhibitive effect on the elevation of cTnI, CK, CK-MB, LDH, and α-HBD during myocardial ischemia." (PMID 29312582, 2017). "Therefore, our study focused not only on the relationship between urinary fluoride concentration and the risk of myocardial enzymes (serum CK, serum CK-MB, serum LDH, serum α-HBD, and serum AST) but also on myocardial ischemia and arrhythmia in a population-based cross-sectional study." (PMID 39944564, 2024).
Obesity (2 papers, 2017 to 2020). Accumulation of substantial excess body fat. "DEGs of NAMPT, TLR9, PTGS2, HBD, and PCSK1N might be associated with obesity." (PMID 29132311, 2017). "And up-regulated genes-NAMPT, TLR9, PTGS2, HBD, and PCSK1N might be associated with obesity risk." (PMID 29132311, 2017).
anemia (1 paper, 2023). A reduction in the number of red blood cells, the amount of hemoglobin, and/or the volume of packed red blood cells. "We report here eight patients on Voxelotor therapy, six of which showed improved hemolytic markers and anemia and demonstrated the appearance of HbD peak on the HPLC chromatogram." (PMID 37153104, 2023).
autoimmune disorders (1 paper, 2023). "Human beta defensin-1(HBD-1) plus its gene polymorphism were linked to some autoimmune disorders." (PMID 36535830, 2023).
basal cell carcinoma (1 paper, 2006). A carcinoma involving the basal cells. "The present work was aimed on the study of hBD gene expression in basal cell carcinoma (BCC) which is the most common cancer in humans." (PMID 16796735, 2006).
chronic gastritis (1 paper, 2019). Inflammation of the stomach that is chronic in nature. "qRT-PCR analysis showed significant up-regulation of HBD-2 gene expression between H. pylori-negative chronic gastritis to H. pylori-positive chronic gastritis." (PMID 31537016, 2019).
colon cancer (1 paper, 2015). "Our hypothesis was that down-regulation of hBD gene expression in colon cancer tissues may be due to the presence of epigenetic modifications, particularly mutations in the hBD exons." (PMID 26038828, 2015). "In the current study, we demonstrated for the first time a clear link between hBD expression/production and colon cancer." (PMID 26038828, 2015). "We demonstrated for the first time a link between hBD expression and colon cancer." (PMID 26038828, 2015). "hBD gene expression and relative protein expression were evaluated by Real-Time polymerase chain reaction (qPCR) and immunohistochemistry, respectively, from 40 normal patients and 40 age-matched patients with colon cancer in Saudi Arabia." (PMID 26038828, 2015). "The other mutations found in the hBD promoter region are predicted to affect the expression/stability of the regulatory regions (5'UTR and 3'UTR) in colon cancer tissues, which explains why the expression of these hBDs were decreased in colon cancer tissues compared with normal tissues." (PMID 26038828, 2015).
Crohn disease (1 paper, 2024). A gastrointestinal disorder characterized by chronic inflammation involving all layers of the intestinal wall, noncaseating granulomas affecting the intestinal wall and regional lymph nodes, and transmural fibrosis. "When tissue and circulating hBD protein levels were analyzed, elevated hBD-3 levels were detected in terminal ileum, and elevated hBD-2 levels were detected in serum samples of Crohn’s disease patients." (PMID 38246944, 2024). "This is in line with the recent evidence that defects in the hBD or SALSA expressions do not necessarily exists in Crohn’s disease, as there is no genetic susceptibility." (PMID 38246944, 2024).
cystic fibrosis (1 paper, 2013). Autosomal recessive disorder caused by pathogenic variants in the CFTR gene (cystic fibrosis transmembrane conductance regulator), which encodes a chloride and bicarbonate channel expressed in epithelial cells, and follow the diagnosis criteria. "Mother was a carrier for the Cystic Fibrosis (delta F508), Factor V Leiden mutations, HbD-Los Angeles and HbQ-India variants." (PMID 23840982, 2013).
diabetes (1 paper, 2025). "Although wounds remained in early stages of regeneration by 10 days, likely due to the combined burden of diabetes and infection, the findings demonstrate a significant shift toward a less inflammatory but more restorative phase upon treatment with hBD-2 hydrogels." (PMID 40663184, 2025).
epilepsy (1 paper, 2012). A brain disorder characterized by episodes of abnormally increased neuronal discharge resulting in transient episodes of sensory or motor neurological dysfunction, or psychic dysfunction. "Notably, hBD-GCs appear to be more numerous under pathological conditions, such as hypoxia-ischemia, experimentally induced epilepsy, and pharmacoresistant temporal lobe epilepsy of humans." (PMID 23144894, 2012).
Erythema (1 paper, 2012). Redness of the skin, caused by hyperemia of the capillaries in the lower layers of the skin. "Since T1Rs are clinically characterized by edema and erythema, we investigated whether the increased hBD expression was due to an increase in cellular infiltration." (PMID 23133681, 2012).
esophageal SCC (1 paper, 2014). "The overexpression of HBD-2 may contribute to esophageal SCC carcinogenesis by the feedback regulation of NFκB." (PMID 25226614, 2014). "Some molecules involved in IL-1β/HBD-2 regulation, such as NFκB and MAPK, have been activated in esophageal SCC." (PMID 25226614, 2014).